CXCR5 (C-X-C motif chemokine receptor 5)
Diseases named in the same sentence as CXCR5 in open-access papers (continued):
Sharing a sentence is not in itself a finding about the gene and the disease.
COVID-19 (42 papers, 2020 to 2025). A disease caused by infection with severe acute respiratory syndrome coronavirus 2. "Fifthly, for B cells, significant downregulation of MCH-II molecules and loss of chemokine receptor CXCR5 were seen in COVID-19 patients with acute necrotizing encephalopathy." (PMID 37848421, 2023). "The COVID-19 patient B cell phenotype was dominated by the loss of CXCR5 and IgD compared with B cells from HDs and RDs." (PMID 32669297, 2020). "Thus, B cell responses—most often characterized by elevated PBs, decreases in memory B cell subsets, enrichment in a T-bet+ B cell subset, and loss of CXCR5 expression—were evident in many hospitalized COVID-19 patients." (PMID 32669297, 2020). "Other potential mechanisms of the RC decoction against the ALI involved the pathways of ribosome and coronavirus disease 2019 (COVID-19); the target genes of inflammatory factors, such as Ccl17, Cxcl17, Cd163, Cxcr5, and Il31ra, and lncRNAs; and the regulations of the respiratory cilia." (PMID 36072401, 2022). "In contrast, the frequency of memory switched CXCR5+ B cells was significantly reduced in COVID-19 and in LC patients." (PMID 39845978, 2024). "They reported that the induction of antigen-specific CD4+CD154+CD137+CXCR5+ peripheral TFH (pTFH) cells by the COVID-19 vaccine was higher in CVID sero-responders than in sero-nonresponders." (PMID 38921811, 2024). "CXCR5 expression was altered in acute and convalescent COVID-19 subjects, whereas the frequencies of CXCR3+ and CCR4+ cells were decreased in both patient groups vs. HC." (PMID 36146713, 2022). "Other studies have demonstrated that CXCR5+ Tfh populations are significantly elevated in individuals recovering from COVID-19 and correlate with robust humoral immunity; however, this previous study did not analyse the regulatory arm in this compartment." (PMID 35027067, 2022). "Another sign of B cell malfunction in COVID-19 is a sharp decrease in the expression of CXCR5, a chemokine receptor responsible for the migration of B cells to B cell areas of peripheral lymphoid organs." (PMID 35632823, 2022). "Adenoid tissues isolated from COVID-19 convalescents were noted to have an increased proportion of CD8+CXCR5+ T cells, additionally expressing markers CD69 and CD103 typical of tissue-resident memory cells." (PMID 36146713, 2022). "Another study showed that the proportion of PD-1+ICOS+ and CD38+HLA-DR+ cells increased within the CXCR5+CD4+ Tfh pool in the circulation in all patients with COVID-19." (PMID 35632823, 2022). "The CD4+ cells were significantly lower, while the total number of CD4+CXCR5+ Tfh cells was significantly higher in COVID-19 patients compared to controls (p < .0001 and p = .03, respectively)." (PMID 35286241, 2022). "Other potential mechanisms involved the ribosome and COVID-19 pathways; the inflammatory factors genes, such as Ccl17, Cxcl17, Cd163, Cxcr5, and Il31ra, and the lncRNAs genes; and the respiratory cilia functions." (PMID 36072401, 2022). "In particular, it was shown that a bronchoscopy of critically ill COVID-19 patients requiring invasive mechanical ventilation (IMV) detected a great quantity of activated CXCR5 co-expressing CD38+CD8+ T cells." (PMID 36146713, 2022). "A chemokine receptor, CXCR5, is responsible for B cell trafficking and is found to be downregulated in B cells in COVID-19 patients." (PMID 35312683, 2022). "Next, we also demonstrated that acute COVID-19 was noted to have upregulated CXCR5 expression on diverse cytotoxic CD8+ T cell subsets." (PMID 36146713, 2022). "Next, we analyzed the CXCR5+ CM Tfh cell populations in patients with COVID-19 and in the control group." (PMID 35337103, 2022). "Of note, we also found Ki67 expression on Tscm CXCR5+HLADR+CD8+ T cells compared with other CD8+ T cell subsets from patients with COVID-19." (PMID 34283810, 2021). "Of note, both the frequency and gMFI of CXCR5 were reduced in pediatric COVID-19 (gMFI only) and MIS-C compared to healthy adults." (PMID 33653907, 2021).
COVID-19 (continued). "B cell frequencies were similar in patients and controls, but the percentage of CXCR5+ B cells was significantly reduced in active COVID-19." (PMID 34614036, 2021). "We also observed a significant decrease in CXCR5 and HLA-DR expression levels in B cells from COVID-19 patients." (PMID 33777054, 2021). "By contrast, this clustering approach identified reduction in CXCR5+ cTFH-like cells (clusters 2 and 3) in COVID-19 participants compared with HDs." (PMID 32669297, 2020). "Specifically, there was an increase in CXCR5+CD45RA– memory T cells among COVID-19 convalescents." (PMID 41376646, 2025). "Similarly, CM CD8+ T cells in COVID-19 convalescents also contained a higher level of CXCR5-expressing cells as compared with control group (6.07% (4.29; 8.76) vs. 3.22% (1.88; 4.67), p < 0.001)." (PMID 36146713, 2022). "Moreover, for COVID-19 convalescents, lower expression levels of CXCR5 on IgD+CD27+ and IgD–CD27+ memory B cells were also noted, which indicates a durable impairment in B cell function during the period of recovery." (PMID 35632823, 2022). "According to the literature and our observation of polyfunctionality of this population, we suggest that the Tscm CXCR5+HLA-DR+CD8+ T cells might have an importance for virus clearance in COVID-19." (PMID 34283810, 2021). "In addition, MSCs alter B cell trafficking phenotype, including downregulation of CXCR4 and CXCR5, that are differentially regulated in COVID-19 (see section “B Cell Trafficking Phenotype section”)." (PMID 34595175, 2021). "CXCR5 expression was also reduced on all major B cell subsets in COVID-19 patients." (PMID 32669297, 2020). "However, we found that the patients with acute COVID-19 had an increased level of CXCR5+ cell within CM and EM compared with healthy controls (6.35% (4.00; 11.83) vs. 3.22% (1.88; 4.67) and 1.60% (0.91; 2.69) vs. 0.85% (0.34; 1.37), p < 0.001 in both cases, respectively)." (PMID 36146713, 2022). "Hence, a long-term increase in peripheral blood CCR6- and CXCR5-expressing CD8+ T cells in COVID-19 convalescents revealed in our study might be considered one of the signals associated with long-COVID alterations in cytotoxic T cell subset composition." (PMID 36146713, 2022). "Increased expression of chemokine and cytokine receptors such as CXCR5, CCR4, CCR5, and CCR7 has been reported in both active and recovered COVID-19 individuals." (PMID 38357647, 2024). "This is in line with several studies trying to understand the immune profile of COVID-19 patients that report elevated frequencies of CD38+ ICOS+ CXCR5+ CD4+ T cells during acute disease." (PMID 37061513, 2023). "SARS-CoV-2 maternal infections display higher frequencies of CXCR5+CD4+ and CCR6+CD4+ T cells and higher plasma concentrations of IL-6 and IL-18, when compared with gestational age–matched COVID-19–vaccinated counterparts." (PMID 37490342, 2023). "Furthermore, we found that the chemokine receptor CXCR5 was significantly decreased in COVID-19 patients, which might lead to inhibition of germinal center reactions and the dysregulated humoral immune responses observed in the early stage of SARS-CoV-2 infection." (PMID 37848421, 2023). "There was an increased percentage of CD11c+ CXCR5- (DN2) cells at day 7 to 28 post vaccination in all groups, with a higher level in COVID-19 experienced than COVID-19-naïve PAD patients." (PMID 36618402, 2022). "Further, chemokine and cytokine receptors (CXCR3, CXCR4, CXCR5, CCR4, CCR5, and CCR7) expression was increased in active COVID-19 and recovered patients." (PMID 36532041, 2022). "Total CD4+CXCR5+ Tfh cells and ICOS+Foxp3-activated Tfh cells increased and ICOS+Foxp3+ Tfr cells decreased in COVID-19 patients, especially in diabetic patients and those with severe disease." (PMID 35286241, 2022).
COVID-19 (continued). "Despite the evaluated levels of circulating memory Tfh cells in both the lymph nodes and spleen of patients with COVID-19, Tfh cells with different phenotypes, CD4+ICOS+, CD4+ CXCR5+, and CD4+ Bcl-6+, were present at decreased levels." (PMID 34696395, 2021). "Surviving patients with COVID-19 had increased levels of PD-L1+CXCR3+CD8+ Teffs and CXCR5+HLA-DR+CD8+ Tscms." (PMID 34283810, 2021). "During acute COVID-19, B cells showed a reduced expression of CXCR3, CXCR5 and integrin β7 according to disease severity, with CXCR3 and CXCR5 level normalization in convalescent subjects." (PMID 34595175, 2021). "EMD group 2, containing mostly HDs and RDs, was enriched for naïve B cells (IgD+CD27−, cluster 10) and CXCR5+IgD−CD27+ switched memory cells (cluster 2), and indeed, clusters 2 and 10 were statistically reduced in COVID-19 patients." (PMID 32669297, 2020). "Comparing COVID-19 and controls at the level of MFI for each subject within each MC and each subset revealed expression patterns highly comparable to CAP, such as decreased HLA-DR and CD11c, and increased PD-L1, PD-1, CD95/Fas, CD38 and CXCR5." (PMID 38077404, 2023). "Induction of antigen-specific CD4+CD154+CD137+CXCR5+ pTFH cells by the COVID-19 vaccine was higher in CVID seroresponder than in non-seroresponder." (PMID 36932291, 2023). "Levels of total CD4+CXCR5+ Tfh cells were significantly increased in the non-diabetic COVID-19 patients compared with healthy volunteers (p = .003) and diabetic COVID-19 patients (p = .01)." (PMID 35286241, 2022). "Primarily, we estimated the CXCR5+ Tfh frequencies within CD3+CD4+CD45RA− memory cell subset and found that COVID-19 convalescent patients had elevated Tfh cell count compared with HC, reflecting the expansion of cell type after acute phase of SARS-CoV-2 infection." (PMID 35723393, 2021). "Notably, we did not detect CXCR5 transcripts in NK cells from our COVID-19 cohort, limiting our ability to directly compare the in vitro and in vivo migratory phenotype." (PMID 41272165, 2025). "Interestingly, Tfh cells’ frequency in COVID-19 was lowered, regardless of COVID-19 severity, but within central memory Th cells, a lower level of CXCR5-expressing CD4+ T cells was found in patients with severe COVID-19 vs. patients with moderate COVID-19." (PMID 36146713, 2022). "Among DN cells, DN1 (FcRL5- CXCR5+) B cells were the dominant subset in both groups of recovered COVID-19 patients, and we did not detect significant differences in the frequencies of DN1, DN2 (FcRL5+ CXCR5-), and DN3 (FcRL5- CXCR5-) B cells between the two groups." (PMID 34936684, 2021). "Additionally, increased frequencies of virus-specific cTfh cells (CD4+CXCR5+OX40+CD40L+) were observed in acute and convalescent COVID-19 cases, and the frequencies of both SARS-CoV-2-specific cTfh cells and S-specific CCR6+CXCR3-cTfh17 cells were closely associated with low disease severity." (PMID 34603308, 2021). "Furthermore, low frequencies of CD45RA-PD-1+CXCR5+cTfh cells were also observed, but elevated frequencies of activated cTfh (CD38+ICOS+) cells were positively correlated with anti-SARS-CoV-2 IgM and IgG titers in hospitalized COVID-19 patients." (PMID 34603308, 2021). "Increased expression of CXCR5 and ICOS on SARS-CoV-2-specific CD4 T cells in mild to severe COVID-19 patients with acute infection has been reported, but none of the studies tested cTfh functionality directly." (PMID 37061513, 2023). "A lower frequency of CD4+CXCR5+ICOS+ Foxp3+ Tfr cells was found in the diabetic patients compared to controls (p = .01) and non-diabetic COVID-19 patients (p = .02)." (PMID 35286241, 2022). "CD4+ and CD8+ T cells in acute COVID-19 patients showed a substantial reduction of CXCR3 and CXCR5 expression, irrespective of disease severity, that is recovered upon convalescence." (PMID 34595175, 2021).
COVID-19 (continued). "However, upon considering a broader spectrum of TFH cells regardless of ICOS expression, CD4+, CXCR5+, and PD-1+ TFH were most abundant in COVID-19 patients with mild disease." (PMID 33361110, 2021).
Autoimmunity (40 papers, 2008 to 2025). The occurrence of an immune reaction against the organism's own cells or tissues. "Investigating exhaustion dynamics of CXCR5+ T cells within autoimmunity is challenging due to the association of PD-1 as an activating and inhibitory receptor." (PMID 36314014, 2022). "In inflammatory disease and autoimmunity, CXCR5+CD8 T cells are implicated in disease progression." (PMID 36314014, 2022). "Furthermore, numerous studies also suggested that an altered balance of blood CXCR5+ CD4+ Tfh cell subsets was closely linked with autoimmunity." (PMID 36761174, 2022). "Genetic risk factors have been newly identified for Sjögren’s syndrome, including IRF5, STAT4, CXCR5, IL12A, HLA-DRA, and BLK, which are linked to autoimmune disorders as well." (PMID 40136761, 2025). "This review summarizes the recent advances in our understanding of the CXCL13/CXCR5 immune axis and its role in vaccination, autoimmunity, and infection with a special focus on its relevance for intrathecal B cell activities in inflammatory CNS diseases." (PMID 36078057, 2022). "Studying CXCR5+CD8 T cells using animal models that perpetuate autoimmunity would explain how these cells respond to ICB and if they initiate disease development." (PMID 36314014, 2022). "CXCR5+ CD8 T cells promote cell lysis in viral infection and in some cancers, while in inflammation and autoimmunity CXCR5+ CD8 T cells function as helper cells, thus promoting disease pathogenesis." (PMID 31275308, 2019). "Further investigation and characterization of CXCR5+PD-1+CD8+ Tfh cells would help to develop new strategies to control autoimmunity by targeting follicular CD8 helper T cells." (PMID 31562329, 2019). "Expansion of circulating CXCR5+ Tfh cells (cTfh) with a B cell helper phenotype in the blood has been described besides pSS patients in a variety of autoimmune conditions such as MS, autoimmune thyroiditis, SLE and especially RA50–55." (PMID 28827539, 2017). "The role of blood CXCR5+CD4+T cells in patients with autoimmunity has been explored, but little is known about the role of circulating CXCR5+CD4+ T cells in patients with chronic HBV infection." (PMID 24655429, 2014). "In this study, we performed an extensive analysis of CXCR5−PD‐1hi cTph and CXCR5+PD‐1hi cTfh cells at the single‐cell level to elucidate outstanding questions on the timing of their emergence during T1D autoimmunity, cellular heterogeneity, and relationship with each other." (PMID 40538220, 2025). "Tfh cells typically express CXCR5, PD-1, and ICOS, and previous studies showed that upregulation of these markers in Tfhcells was associated with abnormally high autoantibody titers in autoimmune patients." (PMID 37901207, 2023). "The circulating CD4+CXCR5+FOXP3+ Tfrs with enhanced suppressive function could alleviate autoimmunity in RA patients by reducing IgG and IgM levels, and the proportion of Tfrs was negatively correlated with the disease severity." (PMID 35474948, 2022). "The reduced expression of CXCR5 by CD11c+ B cells described here, argues in favor of the extrafollicular generation of CD11c+ B cells in autoimmunity, especially in active disease, and the enrichment of autoreactive clones due to the lack of proper selection outside germinal centers." (PMID 33777025, 2021). "As such, BBR’s suppressive effect on CXCR5+ Tfh cell populations, while potentially beneficial for autoimmune pathologies, also raises concern that prolonged use could impact a patient’s ability to mount effective beneficial primary adaptive immune responses." (PMID 33805383, 2021). "Differences in CXCR5 expression on peripheral T cells have been observed in non-infectious causes of altered T cell dynamics (autoimmunity and primary immunodeficiency)." (PMID 28580437, 2017).
Autoimmunity (continued). "The circulating CD4+CXCR5+FOXP3+ Tfrs with enhanced suppressive function could alleviate autoimmunity in RA patients by reducing IgG and IgM levels, and the proportion of Tfrs was negatively correlated with the disease severity, which provided a novel insight into RA pathogenesis." (PMID 35474948, 2022). "Thus, CXCL13/CXCR5-associated immune activities of SLO involve a gradually discovered arsenal of players contributing to adaptive humoral immunity, their balance being of utmost relevance for infection control and prevention of autoimmunity from top to bottom." (PMID 36078057, 2022). "Tfh are a subset of CD4+ T cells in the germinal center that express CXCR5 and provide help to B cells for antibody production; circulating Tfh (cTfh) are considered a counterpart of Tfh, and alterations in the frequency of cTfh have been described in several autoimmune conditions." (PMID 35087513, 2021). "Characterization of CXCR5+CD8 T cell exhaustion in chronic or high antigen environments is limited for infection, cancer and autoimmunity." (PMID 36314014, 2022). "This review will detail the functionality of CXCR5+CD8 T cells in cancer and autoimmunity with potential repercussions during immune checkpoint blockade therapy discussed." (PMID 36314014, 2022). "Our study can also constitute a starting point for approaching the role of CXCR5+ and IL21+ CD8 T-cells (Tfc) in the context of autoimmunity." (PMID 33603079, 2021). "To date, CXCR5+CD8+ T cells have only been shown in chronic infection, cancer and autoimmunity, all settings where there is antigen persistence." (PMID 34326833, 2021). "At approximately 1 year of age, CD4-ERα KO mice spontaneously showed mild autoimmunity with increased autoantibody production and CD4+CD44+CXCR5+Bcl-6+ TFH cells in the mesenteric lymph nodes and spleen." (PMID 30988419, 2019). "Higher levels of activated CXCR5+ peripheral TFH cells were reported previously for CVID patients in particular in patients with non-infectious manifestations (autoimmunity and granulomatous disease), suggesting a functional significance of this association." (PMID 36932291, 2023). "CXCR5+CD4 T follicular helpers (CD4 Tfh) have received most of the limelight for their contribution to germinal center migration, functionality, and B cell help within infection, cancer, and autoimmunity." (PMID 36314014, 2022). "Because low CCR7 and high PD-1 expression have been observed in circulating TFH from patients with autoimmune conditions, we examined the TFH subsets considering the level of expression of these molecules on the surface of CXCR5+CD4+ T cells from CVID patients and N controls." (PMID 27069935, 2016). "CXCR5+CD8 T cells have slowly come into focus with their unique ability to provide B cell help within germinal centers similar to CD4 Tfh and also maintain a cytolytic capacity in infection, autoimmunity and tumor microenvironments resembling CD8 T effector cells." (PMID 36314014, 2022). "Most circulating and intrahepatic PD-1hiICOShi CD4+ Tfh1-like cells did not express CXCR5 and therefore resembled CXCR5–CXCL13+ peripheral helper cells that infiltrate tumors and tissues inflamed by autoimmunity." (PMID 40956619, 2025).